LINC00324 (long independently transcribed non-coding RNA 324)
Synonyms: FLJ34790; MGC104931; TP53LC03; RNA00324; C17orf44; NCRNA00324
Gene: Long non-coding RNA gene on chromosome 17 (8,220,616 to 8,224,079, reverse strand). Ensembl gene ENSG00000178977.
Gene Ontology:
Molecular function: triplet codon-amino acid adaptor activity
Biological process: translation
Diseases named in the same sentence as LINC00324 in open-access papers:
LINC00324 is named in the same sentence as 14 diseases in open-access papers, as found by Europe PMC text mining. Sharing a sentence is not in itself a finding about the gene and the disease. The quoted sentences say what the papers report.
gastric cancer (4 papers, 2020 to 2022). A primary or metastatic malignant neoplasm involving the stomach. "LINC00324 is upregulated in gastric cancer, and its upregulation significantly correlates with the TNM stage, tumor size, and lymph node metastasis." (PMID 32369777, 2020). "Recent studies have suggested that LINC00324 plays a pivotal role in modulating osteosarcoma and gastric cancer progression." (PMID 32305959, 2020). "LINC00324 overexpression in gastric cancer correlates with larger tumor sizes, lymph node metastasis, and low survival rate." (PMID 33318312, 2020). "For instance, LINC00324 overexpression enhances cell proliferation, migration, and invasion in gastric-cancer and inhibits apoptosis in vitro; further, it also facilitates tumor growth in vivo." (PMID 32369777, 2020). "In addition, expression of LINC00324 has been validated as an independent predictive factor of overall survival and disease-free survival among patients with gastric cancer." (PMID 32369777, 2020).
lymph node metastasis (3 papers, 2018 to 2022). "LINC00324 is aberrantly expressed in 11 cancers, and dysregulated LINC00324 is also associated with poor prognosis and clinical characteristics, including tumor size, lymph node metastasis, tumor TNM stage, and clinical stage in cancer patients." (PMID 36620587, 2022). "In NSCLC, LINC00324 upregulation was associated with a higher rate of lymph node metastasis." (PMID 36620587, 2022). "The overexpression of LINC00324 was correlated with advanced TNM stage, larger tumor size, and lymph node metastasis as well as poor prognosis." (PMID 29915327, 2018). "Multivariate analysis including gender, age, TNM stage, Lymph node metastasis, tumor size, HP infection, and LINC0324 expression revealed that TNM stage (P < 0.001) and LINC00324 expression (P < 0.001) were independent prognostic factors of DFS and OS." (PMID 29915327, 2018).
breast carcinoma (2 papers, 2020 to 2022). "LINC00324 can thus potentially act as an early diagnostic marker and a novel therapeutic agent for breast cancer." (PMID 32305959, 2020). "Aberrant expression of LINC00324 is associated with malignant clinicopathological characteristics of the disease and suggests a possible regulatory capacity in breast cancer." (PMID 32305959, 2020). "Mechanistically, LINC00324 inhibits the EMT process in breast cancer by sponging miR-10b-5p and, as a result, restraining the progression of breast cancer." (PMID 32305959, 2020). "Level of LINC00324 was significantly lower in breast cancer tissues compared to adjacent normal tissues." (PMID 32305959, 2020). "Downregulation of LINC00324 expression was observed in the T stage of TNM breast cancer classification and was closely related to the increase in tumor size and volume." (PMID 32305959, 2020). "Given that miRNA may be a target for anti-cancer therapy, overexpression of LINC00324 could be considered as a new therapeutic approach for restricting breast cancer activities." (PMID 32305959, 2020).
lung adenocarcinoma (2 papers, 2020). A carcinoma that arises from the lung and is characterized by the presence of malignant glandular epithelial cells. "LINC00324 levels are markedly up-regulated in lung adenocarcinoma, and LINC00324 overexpression promotes the progression of lung adenocarcinoma through upregulation of Akt1 via sequestering miR-615-5p." (PMID 33318312, 2020). "LINC00324 is also overexpressed in lung adenocarcinoma and osteosarcoma." (PMID 32369777, 2020).
osteosarcoma (2 papers, 2020). A usually aggressive malignant bone-forming mesenchymal neoplasm, predominantly affecting adolescents and young adults. "Overexpression of LINC00324 is closely associated with tumor size, distant metastasis, TNM stage, differentiation degree, and poor prognosis among patients with osteosarcoma." (PMID 32369777, 2020). "In osteosarcoma, LINC00324 overexpression increases WDR66 expression, thereby promoting tumor cell proliferation and migration in vitro." (PMID 32369777, 2020).
glioblastoma (1 paper, 2024). The most malignant astrocytic tumor (WHO grade IV). "The expression of LINC00324 in glioblastoma was significantly higher than that in other pathological types, as well as in IDH1-WT and 1p19q non-codel groups." (PMID 38530810, 2024).
glioma (1 paper, 2024). A benign or malignant brain and spinal cord tumor that arises from glial cells (astrocytes, oligodendrocytes, ependymal cells). "To gain further insight into the biological pathways associated with glioma pathogenesis and stratified by LINC00324 expression level, we performed Gene Set Enrichment Analysis (GSEA)." (PMID 38530810, 2024). "We assessed the expression of LINC00324 of LINC00324 in glioma patients based on data from The Cancer Genome Atlas (TCGA) and Genotype-Tissue Expression (GTEx) to identify pathways involved in LINC00324-related glioma pathogenesis." (PMID 38530810, 2024). "Our assessment of LINC00324 mRNA expression in glioma revealed that LINC00324 plays an essential role in glioma pathogenesis, although further experimental studies are needed for confirmation." (PMID 38530810, 2024). "Based on our findings, we observed differential expression of LINC00324 between tumor and normal tissues in glioma patients." (PMID 38530810, 2024). "Our analysis of overall survival (OS) and disease-specific survival (DSS) indicated that glioma patients with high LINC00324 expression had a poorer prognosis compared to those with low LINC00324 expression." (PMID 38530810, 2024). "Additionally, the JAK/STAT3 signaling pathway, NF-κB signaling pathway, and immune microenvironment disruptions appear to be key pathways involved in the regulation of LINC00324 in glioma." (PMID 38530810, 2024). "Moreover, LINC00324 expression was generally upregulated in IDH1 wild-type glioma patients with worse prognosis, suggesting that LINC00324 may be involved in the mechanism of glioma IDH mutation and tumor metabolic reprogramming." (PMID 38530810, 2024). "To investigate whether LINC00324 may influence immune cell recruitment in the tumor microenvironment and subsequently impact glioma prognosis, we conducted an analysis of the relationships between LINC00324 expression and immune infiltration in gliomas." (PMID 38530810, 2024). "Similarly, HAVCR2, a gene encoding TIM-3, was positively correlated with the expression of LINC00324, which may regulate immune activity through the GALECTIN signaling pathway in the glioma immune microenvironment." (PMID 38530810, 2024).
melanoma (1 paper, 2021). A malignant, usually aggressive tumor composed of atypical, neoplastic melanocytes. "According to our study, coexpression of CCR2, CFLAR, PRKCQ, and LINC00324 was associated with autophagy in melanoma." (PMID 34250091, 2021).
rheumatoid arthritis (1 paper, 2023). A chronic, systemic autoimmune disorder characterized by inflammation in the synovial membranes and articular surfaces. "Linc00324 is significantly increased in peripheral blood mononuclear cells of rheumatoid arthritis (RA)." (PMID 37382270, 2023).
cancer (11 papers, 2020 to 2024). A tumor composed of atypical neoplastic, often pleomorphic cells that invade other tissues. "LINC00324 is a long-stranded non-coding RNA, which is aberrantly expressed in various cancers and is associated with poor prognosis and clinical features." (PMID 38530810, 2024). "Some researchers believe LINC00324 can be regarded as a promising candidate for the development of diagnostic and prognostic panels, what’s more, can be used as a therapeutic target for a wide range of cancers." (PMID 36923797, 2023). "Aberrant expression of LINC00324 was significantly associated with oncogenic risk in 11 cancers." (PMID 36620587, 2022). "Our results suggest that LINC00324 expression is abnormally prominent in tumor samples and regulates cancer progression through biological responses such as apoptosis." (PMID 38530810, 2024). "In the available studies, LINC00324 has been shown to play a role through the regulatory axis in a variety of cancer cells and is considered a promising marker for tumor prognostic properties." (PMID 36881404, 2023). "The abnormal expression of LINC00324 is closely related to the clinicopathological characteristics of various tumors and the prognosis of cancer patients." (PMID 36620587, 2022). "Highly expressed LINC00324 promotes cancer development by recruiting transcription factors to increase downstream gene transcription." (PMID 36620587, 2022). "LINC00324 acts as a miRNA sponge to affect the translation of nine downstream mRNAs, thereby promoting cancer phenotype and malignancy." (PMID 36620587, 2022). "LINC00324 is upregulated in cancer tissues and cell lines in the respiratory system, including NSCLC, NPC, and LAC." (PMID 36620587, 2022). "In conclusion, dysregulated LINC00324 directly or indirectly has broad and complex effects on cancer development." (PMID 36620587, 2022). "Although no relevant studies have been conducted in CM, LINC00324 has been shown to be overexpressed in a variety of cancer types and to be associated with pathologic features and risk stratification." (PMID 38364250, 2024). "Linc00324 is over-expressed in a variety of cancer cell lines and tumoral tissues." (PMID 36923797, 2023). "However, since a large body of current research has focused on the function of LINC00324 in promoting cancer development, the relationship between LINC00324 and clinical features has only been documented in a few cancer types." (PMID 36620587, 2022). "In addition, LINC00324 can participate in multiple important signaling pathways and promote the development of cancer." (PMID 36620587, 2022). "Although these findings suggest that LINC00324 suppresses the development and progression of diverse cancers that already exist, there is no proof to associate LINC00324 with the initial onset of cancer." (PMID 32305959, 2020). "LINC00324 is dysregulated in a number of cancers and exerts tumor-promoting functions." (PMID 33318312, 2020). "LINC00324 modulates the PI3K/AKT signaling pathway and promotes cancer development in NPC, NSCLC, and LAC." (PMID 36620587, 2022). "In line with this, previous reports were also unable to find the correlation of LINC00324 and LOC100507053 expression within the cancer patients’ age." (PMID 35237522, 2022). "LINC00324 regulates the cell cycle pathway in IOT and CRC to promote cancer development." (PMID 36620587, 2022).
tumor (10 papers, 2018 to 2024). "In RB, LINC00324 upregulation was associated with a more advanced tumor-node-metastasis (TNM) stage and a higher degree of optic nerve invasion." (PMID 36620587, 2022). "Combined plots were used to illustrate the expression of LINC00324 in normal and tumor samples, revealing significant differences between the two." (PMID 38530810, 2024). "In GC, LINC00324 upregulation was significantly associated with a more advanced TNM stage, larger tumor, and a higher rate of lymph node metastasis." (PMID 36620587, 2022). "In the reproductive system, abnormally high expression of LINC00324 was also present in tumor tissues and cell lines of IOT." (PMID 36620587, 2022). "Intriguingly, the findings of our work are in line with a recent study reporting that LINC00324 expression is elevated in PTC, and silencing of LINC00324 exhibits a tumor-inhibition role in PTC cells." (PMID 33318312, 2020). "LINC00324 exerts tumor-promoting effects through 7 ceRNA axes." (PMID 36620587, 2022). "LINC00324 exerts oncogenic actions during tumorigenesis and tumor progression." (PMID 32369777, 2020). "The knockdown of LINC00324 decreased RB cell proliferation, colony formation, migration, and invasion, and promoted apoptosis and cell cycle arrest in vitro as well as hindered tumor growth in vivo." (PMID 32369777, 2020). "In this study, we found that LINC00324 was significantly upregulated in GC tissues compared with the corresponding adjacent normal tissues and the upregulation of LINC00324 was also associated with advanced TNM stage, larger tumor size, lymphatic metastasis, and poor prognosis of GC patients." (PMID 29915327, 2018). "LINC00324 may exert tumor-promoting functions in MM through targeting the miR-512-3p/ZNF566 axis." (PMID 33193574, 2020). "LINC00324 recruits HuR to enhance mRNA stability of WDR66 and FAM83B, thereby promoting tumor development." (PMID 36620587, 2022). "Based on this evaluation, LINC00877, SLC25A5-AS1, ILF3-DT, LRRC75A-AS1, LINC00324, CD27-AS1, ZFAS1, SNHG5, MIR762HG, and SNRK-AS1 were the top significantly downregulated tumor suppressor candidates in MCL cases." (PMID 36359790, 2022).
LINC00324 also shares sentences with these, for which no sentence is quoted: infection (1 paper); metastasis (1); retinoblastoma (1).